HSPA5 (heat shock protein family A (Hsp70) member 5)
Diseases named in the same sentence as HSPA5 in open-access papers (continued):
Sharing a sentence is not in itself a finding about the gene and the disease.
cancer (continued). "HSPA5 shows high expression among above entry proteins even though CTSL expression shows comparable high in both malignant cancers and corresponding normal samples, demonstrating the significance of viral invasion by HSPA5." (PMID 37275848, 2023). "Once again, HSPA5 expression showed high in almost healthy tissues and upregulated in most cancer tissues, suggesting that all the organs can be invaded, high susceptibility to SARS-CoV-2, and severity to diseases in those people bearing cancers." (PMID 37275848, 2023). "Heat shock protein family A member 5 (HSPA5) increased by activation of ATF4 inhibits lipid peroxidation in ferroptosis by protecting against GPX4 degradation in cancer cells." (PMID 37458878, 2023). "Above all, HSPA2 and HSPA5 expression levels were found to be significantly downregulated or upregulated in cancer tissues compared with normal tissues." (PMID 36982218, 2023). "OLFM4, Histone H3, HTT activate HSPA5, an important molecule that tends to lead to cancer metastasis." (PMID 38304289, 2023). "In this study, we will review the recent research progresses of cell surface HSPA5 functions, expressions, and the mechanisms/pathways of cancers and SARS-CoV-2 invasion." (PMID 37275848, 2023). "In support of the protective role of HSPA5 against ferroptosis, it has been shown that the suppression of the ATF4–HSPA5 axis in erastin-mediated ferroptosis in cancer cells enhanced the lipid peroxidation and ferroptotic cell death." (PMID 36976734, 2023). "HSPA5, heat shock protein family A (Hsp70) member 5, was found to resist ferroptosis in cancer cells." (PMID 36814575, 2023). "Altogether, HSPA5 expression implied the association, roles, and clinical significance in SARS-CoV-2 invasion in cancer patients." (PMID 37275848, 2023). "In vitro and in vivo studies found that silencing of HSPA5 expression in cancer cells inhibits tumor cell metastasis." (PMID 35678681, 2022). "Multivariate Cox regression showed that seven cancer-essential FRGs (ISCU, NFS1, MTOR, EIF2S1, HSPA5, AURKA, and RPL8) were significantly associated (p<0.05) with OS." (PMID 35756689, 2022). "After multivariate and LASSO analyses, seven cancer-essential FRGs (ISCU, NFS1, MTOR, EIF2S1, HSPA5, AURKA, and RPL8) were used to construct the risk model." (PMID 35756689, 2022). "Firstly, The Cancer Genome Atlas (TCGA) database was applied to analyze the expressions of HSPA5 in different cancer types, especially in BC." (PMID 36193502, 2022). "Like embryonic and cancer stem cells, high HSPA5 expression has been detected in hematopoietic stem cells (HSCs)." (PMID 36286039, 2022). "The results showed that the unfolded proteins HSPA5, HYOU1, and PDIA4 were associated with survivability in cancer, and HSPA5 was positively and significantly correlated with CD47, and induced by CD47 in OSCC cells lines." (PMID 35678681, 2022). "Growing evidence showed that HSPA5 mediated ferroptosis resistance and negatively regulated ferroptosis in cancer cells." (PMID 35652069, 2022). "Herein, we firstly found that the expression of HSPA5 was upregulated in most cancers, including BC." (PMID 36193502, 2022). "Surprisingly, the mRNA expressions of HSPA5 are much higher than those of ACE2 in both malignant tumors and normal samples across almost kinds of cancer types." (PMID 33767597, 2021). "Concordantly, pronounced tumor supportive properties were described for HSPA5 in different cancer entities including BC in vivo and in vitro." (PMID 34007022, 2021). "By analyzing patient malignant tissues of different types of cancers, we found that low tissue specificity for the HSPA5 mRNA level is detected in all by RNA-seq." (PMID 33767597, 2021). "Then, we compared to the HSPA5 mRNA expression profile across all tumor samples and their paired normal tissues in 31 types of cancers using the GEPIA dataset." (PMID 33767597, 2021).
cancer (continued). "Cancer patients in survival analysis were divided into high expressed and low expressed groups using median HSPA5 expression and analyzed by overall survival (OS) Kaplan-Meier plots." (PMID 33767597, 2021). "HSPA5 also responds to cell stress mechanisms by promoting protein refolding in the endoplasmic reticulum in cancers or virally-infected cells." (PMID 34220925, 2021). "Higher expression of HSPA5 significantly decreased patient survival in OS in 7 types of cancers, including ACC, BLCA, GBM, HNSC, KIRP, LIHC, UVM." (PMID 33767597, 2021). "It has been demonstrated that HA15 specifically targets the chaperone BiP/GRP78/HSPA5 and induces ER stress, leading to cancer cell death through the simultaneous induction of autophagy and apoptosis." (PMID 33498201, 2021). "Decrease in expression of HSPA5/GRP78, which halts viral entry into the cells and decreases cancer metastasis while enhancing apoptosis." (PMID 33540625, 2021). "Decreasing HSPA5 expression will provide a strategy potentially to prevent COVID-19, especially those with malignant tumors." (PMID 33767597, 2021). "In this study, the differences in HSPA5 expression in various types of normal and cancer tissues were evaluated." (PMID 33767597, 2021). "Data from GEPIA (Gene Expression Profiling Interactive Analysis, a public database newly developed by the Chinese for cancer and normal gene expression profiling) reveal that HSPA5 is markedly upregulated in CRC." (PMID 33997035, 2021). "Understanding of the HSPA5 expressions in different normal tissues and malignant tumors is important." (PMID 33767597, 2021). "In the current study, HSPA5 has been found to be expressed ubiquitously in normal tissues and significantly increased in 14 of 31 types of cancer tissues." (PMID 33767597, 2021). "In the cancer cell lines, HSPA5 RNA expressions were enhanced, compared to the matched normal tissues (data not shown)." (PMID 33767597, 2021). "For example, decreasing HSPA5 expression would be the potentials to prevent COVID-19, especially those with malignant tumors." (PMID 33767597, 2021). "And it has been reported that the high expression of HSPA5 can protect cancer cells from immune surveillance, and inhibition of its expression can promote cell apoptosis and inhibit tumor growth." (PMID 33228592, 2020). "Engrafting both LX2-stellate cells and HepG2-cancer cells led to a significant increase of collagen staining and mRNA-expression of collagen, HSPA5, and spliced XBP1 compared to scaffolds that were only engrafted with LX2-cells." (PMID 33103995, 2020). "In fact, large EVs are also enriched in other proteins that affect glutamine metabolism, such as HSPA5 (GRP78), which was recently demonstrated to promote c-Myc-mediated glutamine flux and proliferation of cancer cells." (PMID 25857301, 2015). "We sought to examine any potential connections between HSPA5 and E1A-mediated anti-cancer activities." (PMID 25301734, 2014). "HSPA5 also mediates other pro-tumor properties of cancer cells." (PMID 41301006, 2025). "It has been previously reported that GRP78 (HSPA5) is commonly expressed in many types of cancer." (PMID 40135833, 2025). "In addition to the regulation of cancer cell stemness and tumor microenvironmental immunosuppression, HSPA5 also plays a role in mediating multidrug resistance." (PMID 41301006, 2025). "Furthermore, analysis of the Clinical Proteomic Tumor Analysis Consortium (CPTAC) dataset revealed significantly higher HSPA5 protein expression in tumor tissues compared to normal tissues in several cancer types." (PMID 40135833, 2025). "As different pathways regulated by PERK and HSPA5 contribute to both cancer progression and therapy resistance, attempts to target PERK and/or HSPA5 individually, jointly, or with other potential targets can yield higher efficacy, particularly in cancers overexpressing HSPA5 or PERK." (PMID 41301006, 2025).
cancer (continued). "HSPA5’s ability to translocate to different locations in the cells seems to promote cell survival and therapy resistance in different cancers, though further understandings of the regulation of HSPA5 localization is needed to exploit csHSPA5 as a therapeutic target." (PMID 41301006, 2025). "In addition, aberrant expression of HSPA5 promotes the progression of breast cancer, pancreatic cancer, and other cancers." (PMID 36982218, 2023). "When HSPA5 over-expression negatively affects cancer treatment outcomes, targeting the link between the UPR and SYK kinase pathways with rationally designed SYK inhibitors may be effective." (PMID 37221596, 2023). "Some of these markers are ubiquitous among cells and cancer types (e.g., HSPA5), but others may be useful only for specific malignancies (e.g., CLGN)." (PMID 37651191, 2023). "Additionally, HSPA5 likely plays a critical role in SARS-CoV-2 invasion/attack in most cancer patients via tumor tissues if HSPA5 is highly expressed." (PMID 37275848, 2023). "Similarly, a natural product of the ritterazine-cephalostatin family, ritterostatin GN1N, showed selectivity for HSPA5 and exhibited a strong anti-cancer efficiency in melanoma." (PMID 37189349, 2023). "HSPA5 contributes to cancer development and progression as an oncogene." (PMID 37385987, 2023). "Therefore, understanding the expression of HSPA5 in various malignant cancers and corresponding normal tissues is essential." (PMID 37275848, 2023). "HSPA5 promotes cancer cell viability, proliferation, and migration in different tumor types." (PMID 37275848, 2023). "Studies have demonstrated that HSPA5 is involved in ferroptosis in various cancers, so we sought to determine whether HSPA5 plays a vital role in BCa." (PMID 36982218, 2023). "In addition, HSPA5 was highly expressed in cancer and positively and significantly correlated with CD47 (R = 0.8432, p < 0.0001)." (PMID 35678681, 2022). "Recently, the ER chaperone BiP/HSPA5/GRP78, a major regulator of the unfolded protein response (UPR), has been found to accumulate in the PM, where it assumes novel functions associated with signal transduction and cancer metastasis, also via Golgi-bypass." (PMID 35465316, 2022). "HSPA5 promotes cancer progression, drug resistance, and metastasis and is a poor prognosis marker." (PMID 35678681, 2022). "Based on TCGA database, we verified the expressions of the HSPA5 in different cancers." (PMID 36193502, 2022). "After that, we further investigated the prognostic values of HSPA5 in a pan-cancer." (PMID 33767597, 2021). "Hence understanding of the HSPA5 expression profiles on different normal tissues and malignant tumors is important." (PMID 33767597, 2021). "Three HSPA proteins were chosen for this comparison, hsc70, glucose regulated protein 78 (Grp78 encoded by HSPA5) and mortalin (encoded by HSPA9), because they are bound, and their complexes disrupted, by the cancer new investigational agent, Sulfur Heteroarotinoid A2 (SHetA2, NSC 726189)." (PMID 34831218, 2021). "Interestingly, the toxicity of HSPA5 inhibitors seems to be restricted to cancer cells as the tested compounds were well tolerated in murine xenograft models." (PMID 34007022, 2021). "Besides, the high HSPA1A, HSPA1B, HSPA4, HSPA5, HSPA8, HSPA13, and HSPA14 expressions were inversely associated with the overall survival rate of patients, tumor grade, and cancer stage." (PMID 34059060, 2021). "HSPA5 is highly expressed on the surfaces of various cancer cells." (PMID 33023006, 2020). "For example, in the HSP70 family, HSPA5 and HSPA6 were positively associated with the hypoxia score in 23 and 20 cancers, respectively, while HSPA1L was negatively associated with hypoxia in 19 cancers." (PMID 33225964, 2020). "Due to this activity, HSPA5 is an emerging therapeutic drug target for cancer." (PMID 31712650, 2019).
cancer (continued). "Among HSP70 family, five members have been especially well examined in association with cancer, which are stress-inducible HSP70s, HSP72 (HSPA1) and HSP70B (HSPA6), and constitutively expressed HSP70s, HSC70 (HSPA8), GRP75/Mortalin (HSPA9), and GRP78 (HSPA5)." (PMID 31878360, 2019). "HSPA5, as a prominent chaperone protein that is overexpressed in a wide range of cancer cells, can be induced under ER stress conditions such as lipid peroxidation and promote cancer progression and therapy resistance." (PMID 31519193, 2019). "Notably, HSPA5 has been reported to be overexpressed in several cancer types, contributing to the acquisition of several phenotypic malignant tumor hallmarks." (PMID 27034162, 2016). "However, the functions of HSPA5 expression in the cells invasion and migration of various cancer types are controversial." (PMID 27034162, 2016). "Molecular chaperone HSPA5 was a key survival factor in development and cancer." (PMID 25609022, 2015). "Because HSPA5 expression is critical for cancer cell mobility, we also examined whether GP78 affected cell migration and invasion." (PMID 25301734, 2014). "Based on the function of HSPA5 in cancer progression, HSPA5 may represent a therapeutic cancer therapy target." (PMID 25301734, 2014). "HSPA5 knockdown has also decreased cancer cell invasion in vitro and metastasis in a mouse model." (PMID 25301734, 2014). "Additionally, HSPA5 also plays a crucial role in various cancers." (PMID 36982218, 2023). "Therefore, we believe that HSPA5 plays an important role in cancer progression." (PMID 35678681, 2022). "However, little is known about the role of ATF4 or HSPA5 in the RET signalling pathway in cancer." (PMID 31534554, 2019). "HSPA5 and Hsp90 play an indispensable role in normal cellular homeostasis by regulating the folding, stability, function of client proteins including protein kinases and transcription factors, many of which are important for the proliferation and survival of cancer cells." (PMID 27684953, 2016). "In addition, we used an HSPA5-overexpressing or control vector ectopically expressed in MDA-MB-231 cells stably expressing E1A (231/E1A) to investigate the effects of HSPA5 on the E1A-mediated suppression of cancer cell migration/invasion." (PMID 25301734, 2014). "In this comparison, the CREB1, FOS, HSPA5, and JUN genes exhibited a significant downregulation in malignant tumors compared to group 1 (p < 0.05) (Analysis 1)." (PMID 40722651, 2025). "Through proteinomics, we identified an interesting protein—HSPA5, which was reported to stabilize GPX4 and inhibit ferroptosis in cancers." (PMID 40603306, 2025). "Further comparisons of BSG, HSPA5 and ACE2, all of which are SARS-CoV-2 receptors and cofactors, we found the expression of BSG to be the highest across almost all kinds of cancer types and normal tissues." (PMID 38484369, 2024). "HSPA5 protein participates in signaling pathways that alleviate SARS-CoV-2 entry and also plays a critical role in the SARS-CoV-2 invasion among cancer patients." (PMID 38974521, 2024). "CLU also protects cancer cells from apoptosis through activating class I phosphoinositide 3-kinase/PI3K-AKT pathways, and HSPA5/GRP78 activation during ER stress." (PMID 38447939, 2024). "The therapeutic significance and prospects in cancers and SARS-CoV-2 entry by targeting HSPA5 will also be discussed." (PMID 37275848, 2023). "HSPA5, highly expressed in the malignant tumors, likely plays a critical role in SARS-CoV-2 invasion/attack in cancer patients via tumor tissues." (PMID 37275848, 2023). "The HSPA5 mRNA levels were significantly higher than those of ACE2 in both cancers and healthy individuals in most cancer types." (PMID 37275848, 2023). "Previous studies have demonstrated the pivotal inhibitory effects of HSPA5, HSPB1, HSF1 and HSPH1 in cancer ferroptosis." (PMID 38041016, 2023). "In cancer cells, inhibition of SIRT1/2 has been reported to induce pro-survival autophagy via acetylation of HSPA5." (PMID 35269765, 2022).
cancer (continued). "Networks of HSP70 or HSP90 (including HSPA8, HSPA5, and HSP90B1) play important roles in the regulation of energy metabolism as well as in cancer cells’ oncogenesis and malignant progression." (PMID 36038612, 2022). "Next, we analyzed the expression values of ADAM17, HSPA5, TMPRSS2, FURIN, and ACE2 in different cancers and corresponding normal individuals." (PMID 35720350, 2022). "ADAM17 mRNA levels were lower than HSPA5 and FURIN but higher than ACE2 and TMPRSS2 in most cancer types." (PMID 35720350, 2022). "The results found that HSPA5, HYOU1, and PDIA4 were involved in the IPA network and when highly expressed, mediated the survivability of cancer." (PMID 35678681, 2022). "To further explore the role of CD47, HSPA5, HYOU1, and PDIA4 genes in cancer, we used the human protein atlas (HPA) database to analyze the expression of these target genes in cancer and their impact on the ability of cells to survive." (PMID 35678681, 2022). "In our study, we analyzed 14 genes that are significantly related to some or most anticancer drugs, such as FANCD2, HSPA5, NFE2L2, ACSL4, and DPP4 in the Cancer Therapeutic Response Portal Database." (PMID 35309947, 2022). "For example, gemcitabine can increase the expression level of heat shock protein 70 family protein 5 (HSPA5), thereby preventing the degradation of the GPX4 protein and ferroptosis in cancer cells." (PMID 36317423, 2022). "We further explored the effect of 5 hub genes (ACSL4, FANCD2, HIF3A, HSPA5, and PSMB7) in 33 kinds of cancer in the TCGA database." (PMID 35652069, 2022). "Surprisingly, the mRNA expressions of HSPA5 are much higher than those of ACE2 in both malignant tumors and normal individuals across almost all kinds of cancer types." (PMID 33767597, 2021). "Heat shock protein A5 (HSPA5, also konwn as GRP78), a member of the HSP70 family, has been found to play an important role in cancer malignancy and anti-tumor therapy." (PMID 33228592, 2020). "Intriguingly, HSPA5 aberrantly expressed in bone-related cancer tissues compared with the normal tissues, whereas ANXA1 expression appeared to be downregulated in cancer." (PMID 33291071, 2020). "The molecular chaperone HSPA5 and HSP90 regulate ferroptosis through modulation of GPX4 degradation in human cancer cells." (PMID 32596160, 2020). "(A) mRNA-expression of ER-stress markers ATF6, ATF4, EIF2AK3, GADD34, EDEM1, DDIT3 and HSPA5, in stellate cells (LX2) co-cultured with cancer cells (HepG2 or Huh7) and treated with 4μ8C or control." (PMID 33103995, 2020). "Other molecules, such as CP, CERLD2, CTSD, HSPA5, HTR3A and TUBB2C, are also frequently up-regulated in cancer." (PMID 28056051, 2017). "Therefore, we compared the expression level of ACE2, HSPA5, BSG in pan-cancers based on TCGA datasets." (PMID 38484369, 2024). "It is also important to note that four independent studies, and ours, on nine cancer cell lines of different origin in total, have identified GRP78/BiP/HSPA5, the ER residential chaperone and one of key central regulators of ER processes, to interact with AGR2." (PMID 34929376, 2022). "What is more, decreased expression of HSPA1, HSPA5, and HSP90 chaperones in BBG-treated tumors most probably deprived the cancer cells of the protective shield against the stressful factors in the tumor microenvironment, which promotes the elimination of cancer cells." (PMID 34964926, 2022). "In addition, HSPA5 was positively and significantly correlated with CD47 expression (p < 0.0001) and induced by CD47-overexpression in the OECM-1 and OC-2 OSCC cancer cell lines." (PMID 35678681, 2022). "Among them, BST2, CALR, DDIT3, HSPA5, and TRIB3 were significantly up-regulated in cancer tissues." (PMID 34580365, 2021).